FGF20 (fibroblast growth factor 20)
Diseases named in the same sentence as FGF20 in open-access papers (continued):
Sharing a sentence is not in itself a finding about the gene and the disease.
deafness (1 paper, 2012). An inherited or acquired condition characterized by the complete loss of the ability to hear from one or both ears. "The viability and hearing loss in Fgf20 knockout mice suggest that FGF20 may also be a deafness-associated gene in humans." (PMID 22235191, 2012). "Our studies also suggest that genetic mutations in FGF20 may result in deafness in humans and that FGF20 may be an important factor for the repair or regeneration of sensory cells in the inner ear." (PMID 22235191, 2012).
depression (1 paper, 2018). "FGF20 gene has been associated with psychiatric disorders such as schizophrenia, attention-deficit and hyperactivity disorder and it has been reported a dysregulation of the FGF system in depressive disorder." (PMID 30241547, 2018). "However, to date no published study have reported the association between FGF20 gene and depression; although some studies have reported association between another FGF system transcripts, such as FGF2, FGF12 and FGFR2 with major depressive disorder." (PMID 30241547, 2018).
ischemic stroke (1 paper, 2025). A stroke disorder caused by obstruction of blood flow to the brain, due to thrombotic (local blood clot formation) or embolic (due to a blood clot or other material traveling from another site) event. "They successfully delivered Fibroblast Growth Factor 20(FGF20) for the treatment of ischemic stroke and collaborated with endogenous miRNAs, such as miR-181b-5p, to enhance neural plasticity." (PMID 41190075, 2025).
myelodysplastic syndrome (1 paper, 2024). A clonal hematopoietic disorder characterized by dysplasia and ineffective hematopoiesis in one or more of the hematopoietic cell lines. "Fgf20 is a downstream target of the Wnt signalling network, as evidenced by its expression in patients with dysregulated Wnt signalling pathway, particularly in myelodysplastic syndromes." (PMID 39129916, 2024).
neuroblastoma (1 paper, 2013). Neuroblastoma (NB) is the most common solid, extracranial childhood tumor. "In contrast to this pro-survival activity, FGF20 treatment of human neuroblastoma cell line SH-SY5Y increases the amount of endogenous SNCA, demonstrating an anti-survival role of FGF20 in dopaminergic neurons." (PMID 24391543, 2013).
ovarian carcinoma (1 paper, 2014). A malignant neoplasm originating from the surface ovarian epithelium. "Our data indicated that FGF20 is expressed in ovarian cancer cell lines and was upregulated in the A2780mTP53 ovarian cancer cells compared to the A2780wtTP53 cells." (PMID 24999452, 2014).
renal dysplasia (1 paper, 2014). Renal dysplasia is a form of renal malformation in which the kidney(s) are present but their development is abnormal and incomplete. "More recently, in vivo transgenic mouse studies showed that Fgf9 and Fgf20 are critical for maintaining nephron progenitor survival; furthermore, FGF20 mutations in human beings were shown to be associated with severe renal dysplasia." (PMID 25478553, 2014).
Waisman syndrome (1 paper, 2012). "In Waisman syndrome, disruption of the 3′ UTR of fibroblast growth factor 20 (FGF20) by a mutation alters the recognition site of mir-433, which results in increased translation of FGF20 and is correlated with increased alpha-synuclein expression." (PMID 23346095, 2012).
tumor (8 papers, 2013 to 2025). "This miRNA has two validated target genes, HDAC6 and FGF20, which have both been implicated in tumor development." (PMID 23890084, 2013). "In this study, we found that FGF20 was specifically detected in FAP(+) CAFs areas that were closely located to PanCK(+) tumor epithelial cells that had positive FGFR2 detection at EOCC tumor invasive margin." (PMID 37964075, 2023). "Significantly higher FGF20 protein levels were observed in the PanCK(-) areas at the EOCC tumor invasive margin than in LOCC tumor invasive margin and normal colon tissue areas." (PMID 37964075, 2023). "FGF20 mRNA levels were significantly upregulated in FAP(+) CAFs at the tumor invasive margin of EOCC compared to LOCC tumors and showed a significant positive correlation (r > 0.6) with 15 of 17 DEGs of WNT signaling in EOCC." (PMID 37964075, 2023). "FGFR2 is upregulated in tumor epithelial cells, while FGF20 is increased in neighbor FAP(+) CAFs at EOCC tumor invasive margin." (PMID 37964075, 2023). "Another tumor model BoC69 developed a remarkably high expression of FGF20 and FGF13 (59- and 18-fold, respectively)." (PMID 34271981, 2021). "Forced expression of FGF20 resulted in increased DNA synthesis, cellular proliferation, in vitro transformation, and in vivo tumor growth." (PMID 24999452, 2014). "Additionally, in silico analyses suggest that miR-195-3p expression regulates FGF20, a growth factor involved in embryonic development, cellular growth, morphogenesis, tissue repair, and tumor growth and invasion." (PMID 40559391, 2025). "Our results found that FGF20 is a downstream target of the WNT signaling in FAP(+) CAFs at EOCC tumor invasive margin and suggested that FGF20 may represent a ligand for FGF receptors." (PMID 37964075, 2023). "In addition, FGF20 protein detection overlapped with FAP protein in PanCK(-) areas at EOCC tumor invasive margin." (PMID 37964075, 2023). "FGF20 is normally only expressed in the adult central nervous system but is expressed in malignant tissues, and therefore it seems reasonable to think that FGF20 is under strong control of miR-433 in normal prostate tissues and that this control is lost during tumor progression." (PMID 23890084, 2013). "Thus, we hypothesized that the focal increased levels of FGF20 in FAP(+) CAFs affect the neighbor tumor epithelial cells at the EOCC tumor invasive margin." (PMID 37964075, 2023). "FGF20 was recently identified and may have a potential role in tumor growth and metastasis." (PMID 24999452, 2014). "We sought to determine how the upregulation of FGF20, a downstream effector of WNT signaling in FAP(+) CAFs, can potentially influence neighbor PanCK(+) tumor epithelial cells at EOCC tumor invasive margin." (PMID 37964075, 2023). "Future functional characterization is warranted to demonstrate the intercellular crosstalk between FAP(+) CAFs producing FGF20 and tumor epithelial cells having enhanced FGFR2 protein levels at the tumor invasive margin of EOCC." (PMID 37964075, 2023). "In conclusion, we identify a unique FAP(+) CAF population that showed WNT signaling upregulation and increased FGF20 levels; while neighbor tumor cells show the upregulation/activation of FGFR2-PI3K/Akt signaling at the tumor invasive margin of EOCC tumors." (PMID 37964075, 2023). "In this tumor, we also observed not only upregulation of FGF ligands (FGF19 and FGF20; 88- and 68-fold, respectively) but also a very strong upregulation of the phospholipase PLA2G4A (345-fold)." (PMID 34271981, 2021). "In detail, FGF1 and FGF10 were downregulated in most of the tumor types whereas FGF3, FGF5, FGF11, FGF19, FGF20, and FGF21 were upregulated in most of the tumor types." (PMID 32596330, 2020). "Thus, we proposed that in neighbor PanCK(+) tumor epithelial cells, FGFR2 is a potential receptor that binds to FGF20." (PMID 37964075, 2023).
tumor (continued). "Spatial transcriptomic analysis of 112 areas of interest, using NanoString GeoMx digital spatial profiling, demonstrate that FAP(+) CAFs at the EOCC tumor invasive margin show a significant upregulation of WNT signaling and higher mRNA/protein levels of fibroblast growth factor 20 (FGF20)." (PMID 37964075, 2023). "In addition, the mRNA levels of CDK1 showed significant positive correlations with FGF20 in FAP(+) CAFs and FGFR2 in PanCK(+) tumor epithelial cells at EOCC tumor invasive margin, but not at LOCC tumor invasive margin." (PMID 37964075, 2023).
cancer (3 papers, 2018 to 2024). A tumor composed of atypical neoplastic, often pleomorphic cells that invade other tissues. "The results of our study revealed that FGF6, FGF20, FGF22, and FGF23 are crucial biomarker proteins that NSP-B specifically targets for the therapy of cancer." (PMID 38434705, 2024).
infection (2 papers, 2024 to 2025). The state of being infected such as from the introduction of a foreign agent such as serum, vaccine, antigenic substance or organism. "Additionally, growth factors such as FGF2 and FGF20 were downregulated only in Delta infection and remained unaffected in Omicron." (PMID 41200555, 2025).
nervous system degenerative diseases (2 papers, 2016 to 2019). "However, there were few reports on the relation between NF-κB and FGF-20, especially in nervous system degenerative diseases." (PMID 27274736, 2016). "Along with V180I mutations in PRNP, genetic variations in other genes, such as lipoprotein(a) (LPA), Leucine-rich repeat kinase 2 (LRRK2), and fibroblast growth factor 20 (FGF20), which are directly or indirectly related to neurodegenerative diseases, were also observed in patients with V180I gCJD." (PMID 31238786, 2019).
brain disease (1 paper, 2020). "Herein, we speculated that FGF20 might have the potential to regulate glial cells in order to control neuroinflammation in brain disease." (PMID 33568994, 2020).
FGF20 also shares sentences with these, for which no sentence is quoted: Parkinson (2 papers); cortical atrophy (1); heart disease (1); renal carcinoma (1); skeletal disease (1); Stroke (1).